UST (uronyl 2-sulfotransferase)
Description:
Sulfotransferase that utilizes 3'-phospho-5'-adenylyl sulfate (PAPS) to catalyze the transfer of a sulfo group to the 2-OH position of uronyl residues in glycosaminoglycan chains. Has mainly activity toward iduronyl residues in dermatan sulfate, and toward glucuronyl residues of chondroitin sulfate. Has little to no activity toward desulfated N-resulfated heparin or N-sulfoheparosan.
Synonyms: CS-2OST; 2OST
Tractability: Antibody: UniProt predicts a signal peptide or a membrane-spanning region. PROTAC: ubiquitination databases record sites on it.
Gene: Protein-coding gene on chromosome 6 (148,746,913 to 149,076,991, forward strand). Ensembl gene ENSG00000111962.
Subcellular location: Golgi apparatus membrane
Pathways (Reactome):
Metabolism: CS-GAG biosynthesis; DS-GAG biosynthesis
Gene Ontology:
Molecular function: 3'-phosphoadenosine 5'-phosphosulfate binding; chondroitin 2-sulfotransferase activity; dermatan 2-sulfotransferase activity; sulfotransferase activity
Biological process: dermatan sulfate proteoglycan biosynthetic process; chondroitin sulfate proteoglycan biosynthetic process
Cellular component: Golgi membrane; membrane; Golgi apparatus
Genetic constraint (gnomAD): Loss-of-function variants: 18 observed, 37.12 expected, observed/expected ratio (o/e) 0.48, 90% interval 0.33 to 0.72. The upper end of that interval is the gene's LOEUF score, 0.72, which puts it in group 2 of 6, group 1 being the genes least tolerant of losing a copy. Missense variants: 422 observed, 455.57 expected, observed/expected ratio (o/e) 0.93, 90% interval 0.86 to 1. Synonymous variants: 197 observed, 175.28 expected, observed/expected ratio (o/e) 1.12, 90% interval 1 to 1.26.
Homologues: Orthologues: chimpanzee UST (99% identical), macaque UST (99% identical), dog UST (98% identical), pig UST (98% identical), mouse Ust (97% identical), rat Ust (81% identical), tropical clawed frog ust (77% identical), guinea pig UST (76% identical), rabbit UST (75% identical), zebrafish usta (66% identical), zebrafish ustb (58% identical), Drosophila melanogaster pip (22% identical). Paralogues in human: HS2ST1 (24% identical).
Diseases named in the same sentence as UST in open-access papers:
UST is named in the same sentence as 12 diseases in open-access papers, as found by Europe PMC text mining. Sharing a sentence is not in itself a finding about the gene and the disease. The quoted sentences say what the papers report.
melanoma (2 papers, 2017 to 2020). A malignant, usually aggressive tumor composed of atypical, neoplastic melanocytes. "To demonstrate that human cancer cells express UST we analyzed the human melanoma cell lines HT168-M1, HT199 and MV3 by qRT-PCR." (PMID 28107390, 2017). "Our concept was supported by the results obtained with siRNA-mediated UST knock-down in human MV melanoma cells." (PMID 28107390, 2017). "Knockdown of UST could significantly reduce migration and adhesion in mouse melanoma cells and pulmonary metastasis in mice." (PMID 32802843, 2020).
major depressive disorder (1 paper, 2020). An episode of depression lasting two or more weeks without an intervening episode of mania. "Similarly, a PGx variant (rs2500535) in the Uronyl 2-Sulphotransferase (UST) gene has been found to be associated with the efficacy of nortriptyline—an antidepressant—in patients with major depressive disorder." (PMID 33050895, 2020).
UST also shares sentences with these, for which no sentence is quoted: cancer (2 papers); breast carcinoma (1); colon adenocarcinoma (1); colorectal cancer (1); dyslipidemia (1); Hypertension (1); metabolic disorders (1); Obesity (1); rectum adenocarcinoma (1); tumor (1).